CABP7 (calcium binding protein 7)
Description:
Negatively regulates Golgi-to-plasma membrane trafficking by interacting with PI4KB and inhibiting its activity.
Synonyms: CALN2; MGC57793
Tractability: Antibody: UniProt places it where antibodies can reach, with high confidence; UniProt predicts a signal peptide or a membrane-spanning region; its Gene Ontology location is reachable by antibodies, with medium confidence.
Gene: Protein-coding gene on chromosome 22 (29,720,003 to 29,731,833, forward strand). Ensembl gene ENSG00000100314.
Subcellular location: Golgi apparatus, trans-Golgi network membrane; Cytoplasm, perinuclear region; Cell membrane
Gene Ontology:
Molecular function: protein binding; calcium ion binding
Cellular component: trans-Golgi network membrane; Golgi apparatus; perinuclear region of cytoplasm; plasma membrane
Genetic constraint (gnomAD): Loss-of-function variants: 9 observed, 19.22 expected, observed/expected ratio (o/e) 0.47, 90% interval 0.28 to 0.82. The upper end of that interval is the gene's LOEUF score, 0.82, which puts it in group 3 of 6, group 1 being the genes least tolerant of losing a copy. Missense variants: 243 observed, 279.51 expected, observed/expected ratio (o/e) 0.87, 90% interval 0.78 to 0.97. Synonymous variants: 123 observed, 108.7 expected, observed/expected ratio (o/e) 1.13, 90% interval 0.98 to 1.31.
Homologues: Orthologues: chimpanzee CABP7 (100% identical), dog CABP7 (100% identical), macaque CABP7 (100% identical), mouse Cabp7 (100% identical), pig CABP7 (100% identical), rat Cabp7 (100% identical), guinea pig CABP7 (93% identical), tropical clawed frog cabp7 (86% identical), zebrafish CABP7 (82% identical), rabbit CABP7 (79% identical), zebrafish cabp7b (77% identical), Caenorhabditis elegans B0563.7 (24% identical), and 11 more. Paralogues in human: CALN1 (64% identical), CABP2 (30% identical), CABP4 (30% identical), CABP5 (29% identical), CABP1 (27% identical), CALM1 (26% identical), CALM2 (26% identical), CALM3 (26% identical), CALML3 (26% identical), CETN2 (23% identical), CETN1 (22% identical), CALML5 (20% identical), and 8 more.
Diseases named in the same sentence as CABP7 in open-access papers:
CABP7 is named in the same sentence as 2 diseases in open-access papers, as found by Europe PMC text mining. Sharing a sentence is not in itself a finding about the gene and the disease. The quoted sentences say what the papers report.
myasthenia (1 paper, 2024). "Because impaired NMJ function may lead to muscle atrophy and weakness as observed in patients with myasthenia, we examined whether muscle-specific deletion of Cabp7 in mice affects muscle homeostasis." (PMID 38327785, 2024).
CABP7 also shares sentences with these, for which no sentence is quoted: age (1 paper).